NGF (nerve growth factor)
Diseases named in the same sentence as NGF in open-access papers (continued):
Sharing a sentence is not in itself a finding about the gene and the disease.
asthma (continued). "Likewise, NTs are detected in other bronchial smooth muscle cells during asthma or sarcoidosis and their relationship with inflammatory cytokines, IL-1β and interferon (IFN)-γ has been established by the induction of NGF, and BDNF mRNA expression and secretion in cell-culture supernatants." (PMID 25418464, 2014). "Thus, elevated NGF might promote AMCC transformation to neuron, which, in turn, would inhibit the synthesis and secretion of EPI and induced bronchoconstriction in asthma." (PMID 22957086, 2012). "Furthermore, sensitization of TRPV1 by inflammatory mediators like prostaglandins (PGs), bradykinin (BK), nerve growth factor (NGF) and LOX metabolites of arachidonic acid may lead to exacerbation of asthma." (PMID 19305794, 2008). "Furthermore, the nerve growth factor (NGF) targeting treatment may be an important therapy for antigen-induced airway hyper responsiveness via attenuation of airway innervation and inflammation in asthma." (PMID 36782330, 2023). "In addition, the reason that the metrics in the Asthma group and the Asthma + PM + Vit D group were not compared in this paper is that the variability of the metrics between the two groups was inconsistent in our results, e.g., the difference in NGF was significant in serum but not in BALF." (PMID 38273268, 2024).
neuropathy (46 papers, 2011 to 2026). A disorder affecting the nervous system that manifests with pain, tingling, numbness, and/or muscle weakness. "In patients with peripheral neuropathy caused by chemotherapy, the decrease in circulating NGF levels was associated with the severity of their neuropathy." (PMID 33338083, 2020). "The data expand the spectrum of disease-relevant alterations in CIP/HSAN, including novel variants in previously rarely recognized entities such as ATL3-, FLVCR1- and NGF-associated neuropathies and previously under-recognized mutation types such as larger deletions." (PMID 37769650, 2023). "Although the NGF binding antibody tanezumab is effective in some pain patients, studies in animal models suggest that NGF itself may be effective in management of pain and neuropathy associated with HIV infection." (PMID 37810432, 2023). "Based on these studies, we proposed a hypothesis that NGF gene therapy for pyridoxine induced neuropathy in dogs could cause hyperalgesia." (PMID 26728069, 2016). "Additionally, they may provoke neuropathies affecting sensory, motor, and autonomic peripheral nerves, including peripheral sensory abnormalities and focal mononeuropathies associated with anti-NGF antibodies, alongside joint-related adverse events." (PMID 41163091, 2025). "All trans retinoic acid alleviates chemotherapy-induced neuropathy by upregulating NGF and retinoic acid receptor β expressions." (PMID 41163091, 2025). "Genetic deletion of NGF or TrkA as well as embryonal immunosuppression of NGF leads to severe neuropathies including reductions in trigeminal ganglia, superior cervical ganglia, and a selective loss of certain nociceptive dorsal root ganglia neurons." (PMID 39204102, 2024). "The connection between low NGF serum levels and the occurrence of severe neuropathy has been well recognized in diabetic patients and in patients with malignancies as well." (PMID 37583905, 2023). "NGF plays a vital role in lipid metabolism and neuronal recovery; lipid metabolism and neuronal recovery are the precursors for retinopathy, neuropathy, and cognitive impairment development." (PMID 37189822, 2023). "VGF is a peptide that is increased with nerve growth factor and highly expressed in the peripheral and central nervous system following neuropathy." (PMID 37298117, 2023). "For example, in a study of 60 patients with bortezomib-neuropathy, patients randomized to receive NGF injections had better nerve conduction studies than those who did not receive NGF." (PMID 35360655, 2022). "To date, there have been three reports of significantly reduced blood NGF levels in diabetic patients with neuropathy." (PMID 33669048, 2021). "NGF is a well-known indicator for predicting the clinical severity and outcome of neuropathy in patients with CIPN." (PMID 34376246, 2021). "Adipose tissue-derived NGF signalling has also been suggested as a mediator of sympathetic innervation, however, a mechanism detailing obesity-related perturbations of NGF in neuropathy is yet to be determined." (PMID 34613819, 2021). "NGF supplementation prevents neuropathy, preserves the liberation of NK1R-expressing cells and benefits the recovery from ischaemia." (PMID 31016359, 2019). "Together, these results indicate that NGF gene therapy can prevent neuropathy in diabetic bone marrow." (PMID 31016359, 2019). "The in vivo experiment indicates that prevention of neuropathy by NGF allows for proper activation of bone marrow cell mobilisation." (PMID 31016359, 2019). "This study shows, for the first time, the presence of neuropathy involving NGF-dependent sensory neurons in bone marrow of type 1 diabetic mice." (PMID 31016359, 2019). "The reduction in distal muscle BDNF and nerve growth factor (NGF) levels indeed correlate with the severity of neuropathy in diabetic patients." (PMID 25512003, 2015).
neuropathy (continued). "Clinical trials with NGF treatment of these two types of neuropathies have to be terminated due to the fact that severe pains were induced in patients, even though symptoms associated with both disorders were ameliorated in early Phase II studies." (PMID 23210531, 2012). "This may result in decreased vitamin D-mediated NGF secretion, which, in turn, could lead to a predominantly small nerve fibers neuropathy." (PMID 36359415, 2022). "Since neuropathy predominantly affects nerves that are dependent on nerve growth factor (NGF) in diabetic patients, exogenous NGF supplementation has demonstrated improved wound contraction, leukocytic chemotaxis, and keratinocyte turnover and, in one study, clinically improved healing." (PMID 34684109, 2021). "The use of anti-NGF antibodies may be effective in treating hyperalgesia in patients with neuropathy and compromised nerve endings." (PMID 29867937, 2018). "NGF may act as a protective factor for Schwann cells, and low levels of NGF may contribute to the development of neuropathy." (PMID 29867937, 2018). "Furthermore, evidence shows that decreased NGF availability may play a major role in the pathogenesis of DN, and animal models of neuropathy respond to the exogenous administration of NGF." (PMID 38645500, 2024). "Thus, the roles of NGF in neuropathy are considerably complicated." (PMID 21211063, 2011). "Recent studies have highlighted the utility of biomarkers, such as NGF and BDNF, in predicting the progression of neuropathy and response to therapy." (PMID 40274830, 2025). "Cross-sectional studies report lower serum NGF in patients with painful or moderate–severe DPN, often inversely correlated with neuropathy scores and with higher malondialdehyde, suggesting convergence between oxidative stress and neurotrophic insufficiency." (PMID 41471293, 2025). "Biomarkers like nerve growth factor (NGF), brain-derived neurotrophic factor (BDNF), and oxidative stress markers (e.g., malondialdehyde) are gaining attention for their utility in early neuropathy detection." (PMID 39857603, 2024). "In diabetic mice, decreased expression of neurotrophic factors, such as nerve growth factor (NGF), in nerve tissue or surrounding tissues was observed at the onset of neuropathy." (PMID 33669048, 2021). "Despite this, we showed that the expression especially of NGF, NGFR, NTRK1, GFRA1, GFAP, and GDNF was upregulated in patients with severe neuropathy as compared to healthy subjects and diabetic patients with subclinical neuropathy." (PMID 30648113, 2018). "NGF is reduced in diabetic patients, and this is accentuated in patients with DSHN, suggesting a connection with this neuropathy." (PMID 28841856, 2017). "Changes in level of nerve growth factor (NGF) have been previously assessed in diabetic patients in relation to diabetic retinopathy and neuropathy." (PMID 25853140, 2015). "The emerging picture point at the hyperactivation of NGF signaling system as a main player in the development of DPN and, possibly, in its progress toward the late structural, irreversible neuropathy." (PMID 23710226, 2013). "NGF promotes functional regeneration of damaged DRG neurons and improves neuropathy in streptozotocin-induced diabetic rats." (PMID 21211063, 2011). "Type 1 diabetic patients without complications (such as neuropathy, retinopathy, or nephropathy) have higher NGF levels than non-diabetic people." (PMID 37189822, 2023). "In contrast, in a study specifically evaluating neuropathic pain in 60 patients treated with platinum or taxane therapy, the 13 patients who developed painful neuropathy had higher NGF levels post-therapy than those without neuropathic pain." (PMID 35360655, 2022). "With this study, we conclude that NGF gene therapy in pyridoxine induced neuropathic dogs does not induce neuropathic pain and facilitates the regeneration of pyridoxine-induced neuropathies in the DRG." (PMID 26728069, 2016).
neuropathy (continued). "In patients with neuropathy in the course of type 2 diabetes, IENF density was significantly lower than in controls, corresponding to early dysfunction of sensory small-diameter nerve fibres and to depletion of SP and nerve growth factor (NGF) in the skin." (PMID 26503622, 2015). "NGF has been demonstrated to counteract the reduction of neurite outgrowth from rat DRG in vitro, induced by cisplatin, vincristine or Taxol and the development of behavioral manifestations of cisplatin-induced neuropathy." (PMID 23190582, 2012). "While apparently safe and well tolerated, the NGF did not improve the severity of neuropathy, measured by neurological examination, quantitative sensory testing and epidermal nerve fiber density." (PMID 23190582, 2012). "We could assume that the amount of NGF was not enough to cause neuropathic pain, but just enough to protect the DRG from the pyridoxine-induced neuropathy." (PMID 26728069, 2016). "NGF as a therapeutic tool has been particularly impacted by this characteristic, even in attempt to treat peripheral neuropathies such as diabetic and HIV-induced neuropathy, two disorders that do not have the delivery barriers to overcome like those of the CNS." (PMID 23210531, 2012).
endometriosis (45 papers, 2011 to 2026). The growth of functional endometrial tissue in anatomic sites outside the uterine body. "An increased expression of NGF and TrkA was found in patients with endometriosis, and immunointensity of NGF in the stroma is highly associated with local nerve fiber density and the severity of deep dyspareunia." (PMID 37893241, 2023). "Recent studies have also revealed that NGF is associated with the mechanism underlying pain in endometriosis." (PMID 33339236, 2020). "In addition, increased NGF expression has been linked to endometriosis and ovarian cancer progression." (PMID 42194047, 2026). "Also, the presence of the inflammatory environment, in general, leads to the production of NGF, which causes neurogenesis in the endometriosis lesion, leading to pain." (PMID 40747182, 2025). "Additionally, metabolites produced by the gut microbiota, including IGF and NGF, play a role in the pain and innervation associated with endometriosis." (PMID 40692689, 2025). "In this study, we present the intra-individual heterogeneity in PGP9.5 nerve bundle density and associated biomarkers of neuroproliferation (NGF, IL-1β), amongst patients who had all three anatomic subtypes of endometriosis at surgery and where at least two subtypes were available for analysis." (PMID 38785989, 2024). "Induction of endometriosis leads to hyperalgesia, which may be associated with a significant increase in NGF, BDNF, and CGRP levels in DRG." (PMID 34806344, 2021). "In addition, it has been reported in a recent study that specific antibodies against neurotrophins, including NGF, may be used to treat and prevent pain and symptoms associated with endometriosis." (PMID 35334511, 2022). "NGF immunointensity in the stroma is also significantly associated with local nerve bundle density and deep dyspareunia intensity Furthermore, suppression of NGF via siRNA in a surgically induced rat model of endometriosis inhibits both endometriotic lesion growth and NFD and reduces hyperalgesia." (PMID 32145751, 2020). "The PF of endometriosis patients contains elevated levels of nerve growth factor (NGF), brain-derived neurotrophic factor (BDNF), and other neurotrophins such as NT-4 and NT-5." (PMID 40692689, 2025). "The clustering analysis, which reveals pain-related genes (SRP14/BMF, GDAP1, MLLT10, BSN, and NGF), further solidifies the genetic basis for the chronic and often debilitating pain experienced by patients with endometriosis." (PMID 41516028, 2025). "NGF expression was significantly reduced in control (6.66, 6.51–7.96) and patient endometrium (6.86, 6.58–7.01) compared to all endometriosis subtypes (p < 0.0001)." (PMID 41516088, 2025). "NGF and neurotrophin-3 (NT-3), are expressed in peritoneal endometriotic implants and in the peritoneal fluid of patients with endometriosis." (PMID 40948761, 2025). "Nevertheless, endometriosis is well-established as an oestrogen-dependent condition and, in experimental models of endometriosis, oestrous cycle stage can impact endometriosis-like lesion characteristics, contents (e.g. NGF and VEGF levels), and nerve density." (PMID 40628399, 2025). "Within lesion types, deep infiltrating endometriosis exhibited lower NGF levels than the patient’s peritoneum (p = 0.0060)." (PMID 41516088, 2025). "In this study, we describe twelve patients undergoing surgery for endometriosis with additional immunohistochemical testing for NGF, IL-1β, and nerve bundle density using PGP9.5." (PMID 38785989, 2024). "Recently, studies have begun to explore the IL-1β-NGF pathway to pain in relation to endometriosis phenotypes." (PMID 38785989, 2024). "This case report highlights the intra-individual heterogeneity in nerve bundle density and NGF and IL-1β expression between anatomic subtypes of endometriosis in patients with greater disease burden." (PMID 38785989, 2024).
endometriosis (continued). "NGF is a critical mediator of pain in endometriosis, often upregulated by inflammatory cytokines such as tumor necrosis factor-α (TNF-α) and interleukin-1β (IL-1β)." (PMID 39324359, 2024). "Dienogest inhibits NGF mRNA and protein production in hEECs expressing PR-A and PR-B, thereby reducing the neural sensitization and pain signaling pathways involved in endometriosis." (PMID 39324359, 2024). "It has been suggested that the neurotrophins such as BDNF, NGF, NT-3 and NT-4/5 generate pelvic pain in endometriosis by the direct alteration of neurological responsiveness, leading to hyperalgesia and allodynia stimuli." (PMID 35334511, 2022). "Neurotrophins, such as BDNF, NGF, NT-3 and NT-4/5, are overexpressed in endometriosis and are involved in the pathophysiology of pain generation in women with endometriosis." (PMID 35334511, 2022). "BDNF, along with NGF and neurotrophins (NT-3, NT-4/5), have been identified in samples of ovarian endometriomas in advanced endometriosis." (PMID 33435569, 2021). "Comparison of the concentrations of neurotrophic factors between groups in phase one showed the highest levels of DRG‐BDNF (p < 0.001) and NGF (p < 0.01) and the lowest levels of serum‐NGF (p < 0.01) in the endometriosis group." (PMID 34806344, 2021). "Inflammatory cells stained with an anti-NGF antibody in the endometriotic interstitium are commonly observed in human endometriosis and rat endometriosis models." (PMID 32145751, 2020). "We analyzed endometriosis- and inflammation-related proteins, such as ER-α, ER-β, CD61, and NGF, in the peritoneum, uterus, and intestine of endometriosis samples." (PMID 33339236, 2020). "Endometriosis-associated pain is related not only to the number and distribution of nerves but also to some neurotrophins, especially BDNF and NGF." (PMID 32145751, 2020). "The chronic pelvic pain marker NGF also showed significantly higher expression in endometriosis-induced animals." (PMID 33339236, 2020). "Mice with endometriosis showed high expression levels of NGF in lesion tissues of the peritoneum, uterus, and intestine." (PMID 33339236, 2020). "In endometriosis, NGF expression is significantly higher in invasive lesions than in noninvasive lesions." (PMID 32145751, 2020). "Increased levels of neurotrophins and their receptors, including NGF and its receptor tyrosine kinase A (TrkA), are also seen in endometrial biopsies of women with endometriosis." (PMID 33132854, 2020). "This is not surprising, as a number of the processes responsible for TRPV1 upregulation and sensitization are found in endometriosis patients, including enhanced ROS concentrations and increased levels of neurotrophins such as NGF." (PMID 33132854, 2020). "The expression of several molecules with neurotrophic effects, including the nerve growth factor, neurotrophin-3 and the brain-derived neurotrophic factor, has been reported in women with endometriosis." (PMID 31491902, 2019). "NGF mRNA was overexpressed in ovarian endometriosis and deep infiltrating endometriosis, significantly higher than that of eutopic endometrium and control." (PMID 28288663, 2017). "They confirmed that the expression of NGF and NT-3 were increased significantly in the peritoneal fluid (PF) of patients with endometriosis, and BDNF was also detected in PF of women with peritoneal endometriotic lesion." (PMID 28288663, 2017). "In endometriosis, the expression of NGF was confirmed using immunohistochemistry in the gland, stroma, and in nerve fibers of endometriosis lesions." (PMID 27519317, 2016). "NGF and BDNF have recently been described in the context of endometriosis associated pain and regulation of neurogenesis in and around the sites of lesions." (PMID 25207642, 2014). "A recent study demonstrated that endometriosis-related pain is mediated through NGF-TrkA signaling." (PMID 40948761, 2025).